CSF1R (colony stimulating factor 1 receptor)
Diseases named in the same sentence as CSF1R in open-access papers (continued):
Sharing a sentence is not in itself a finding about the gene and the disease.
rheumatoid arthritis (16 papers, 2010 to 2025). A chronic, systemic autoimmune disorder characterized by inflammation in the synovial membranes and articular surfaces. "The second ligand of CSF1R, IL-34, is a recently discovered inflammatory cytokine, has associations with various rheumatic conditions such as rheumatoid arthritis, systemic lupus erythematosus, and SS." (PMID 40809841, 2025). "Specifically, chronic inflammation caused by increased activity of macrophages due to increased CSF1R response is present in many autoimmune disorders such as rheumatoid arthritis, inflammatory bowel disease, and autoimmune nephritis, among others." (PMID 30551596, 2018). "Preliminary safety results from phase 1 and 2 studies have been reported for CSF1R inhibitor monotherapy in a variety of settings, including healthy subjects and patients with rheumatoid arthritis, cHL, or advanced solid tumors." (PMID 28716061, 2017). "CSF-1R is overexpressed in the synovium of patients with severe synovitis and a CSF-1R antibody was found to protect bone and cartilage in the collagen-induced mouse model of rheumatoid arthritis." (PMID 39485774, 2024). "Imatinib decreases the proliferation of rheumatoid arthritis synovial cells, suggesting that CSF1R inhibition could potentially mitigate rheumatoid arthritis-induced bone damage." (PMID 32801364, 2020). "A FPA008 trial in 12 rheumatoid arthritis patients and a phase 1 study of ARRY-382 in cancer patients have been reported as meeting abstracts and show that CSF1R inhibition leads to increased serum CSF1 and/or IL-34 levels and diminished NTX228,229." (PMID 32801364, 2020).
pancreatic ductal adenocarcinoma (15 papers, 2014 to 2025). An infiltrating adenocarcinoma that arises from the epithelial cells of the pancreas. "CSF-1/CSF-1R blockade has also been shown to reprogram tumour associated macrophages, and enhance the response to checkpoint immunotherapy in a pancreatic ductal adenocarcinoma model." (PMID 35359423, 2022). "Zhu demonstrated in vivo that interrupting signaling by the myeloid growth factor receptor CSF1R in a mouse model of pancreatic ductal adenocarcinoma (PDAC) can effectively reprogram macrophage reactions, causing enhanced antigen presentation and antitumor T cell responses." (PMID 34178625, 2021). "Furthermore, colony stimulating factor 1 receptor (CSF-1R) inhibitors, which selectively target CSF-1R, and are predominantly expressed by monocytes and macrophages, result in reduced M2 MΦ polarization and enhanced survival in a pancreatic ductal adenocarcinoma (PDAC) mouse model." (PMID 40227806, 2025). "By targeting the colony-stimulating factor-1 receptor (CSF-1R) or CXCR2, the inhibition of TAM recruitment resulted in a STAT3-dependent decrease in CSC numbers in a mouse model of pancreatic ductal adenocarcinoma (PDAC)." (PMID 36679900, 2022). "Moreover, blockade of CSF1/CSF1R signaling by GW2850 and PLX3397 CSF1R inhibitors or by anti-CSF-1 not only blocked TAM and M-MDSC recruitment, but also killed CD206high TAMs and reprogrammed the remaining TAMs to support anti-tumor immune activities in murine ductal pancreatic adenocarcinoma." (PMID 27886105, 2016).
renal cell carcinoma (15 papers, 2012 to 2025). "The CSF1R gene has previously been studied and linked to renal cell carcinoma as a potential therapeutic target in patients." (PMID 28178311, 2017). "When CSF-1 and CSF-1R are coexpressed in renal cell carcinoma and TEC aids in RCC survival and inhibition of apoptosis." (PMID 33414786, 2020). "Binding co-expression of CSF1/CSF1R derived from renal cell cancer enhances cancer cell growth." (PMID 38287102, 2024). "Sunitinib is a multi-kinase inhibitor that targets VEGFR-1/2/3, PDGFRα/β, c-Kit, colony-stimulating factor 1 receptor (CSF1R), RET, and FLT3, it has been approved for treating renal cell carcinoma and imatinib-resistant gastrointestinal mesenchymal tumor (GIST)." (PMID 40346640, 2025). "For instance, the CSF-1/CSF-1R axis could induce phosphorylation and activation of STAT3, which promotes cell survival and proliferation in renal cell carcinoma." (PMID 31565097, 2019).
acute myeloid leukemia (14 papers, 2013 to 2026). Acute myeloid leukemia (AML) is a group of neoplasms arising from precursor cells committed to the myeloid cell-line differentiation. "For instance, AI deep learning models have successfully identified the myeloid lineage markers CD86 and CSF1R as potential therapeutic targets for acute myeloid leukemia." (PMID 40904456, 2025). "In acute myeloid leukemia (AML), cells that express CSF1R support cancer cells by secreting hepatocyte growth factor (HGF) and other cytokines that help cancer cell survival and proliferation." (PMID 32801364, 2020). "RUNX1/ETO, which causes acute myeloid leukemia (AML), acts as a dominant-negative repressor of RUNX1 target genes, including colony-stimulating factor 1 receptor (CSF1R/c-fms), GM-CSF, tumor suppressor p14(ARF) and the retinoic acid receptor β (RARB)." (PMID 23860209, 2013). "GATA2, CEBPA and CSF1R have been reported in MDS and acute myeloid leukemia (AML)." (PMID 27959900, 2016).
cervical cancer (14 papers, 2012 to 2026). A primary or metastatic malignant neoplasm involving the cervix. "This association between TSC-22 and CSF-1R could be used as a novel therapeutic target and prognostic marker for cervical cancer." (PMID 29228668, 2017). "To investigate other roles of TSC-22 in cervical cancer, we performed yeast two hybrid (Y2H) screening, and showed that CSF-1R directly interacts with TSC-22." (PMID 29228668, 2017). "In contrast, we determined that CSF-1R expression was upregulated in cervical cancer cell lines compared to the normal cervical cell line." (PMID 29228668, 2017). "Knockdown of CSF-1/CSF-1R increased apoptosis and reduced proliferation and migration of cervical cancer cells." (PMID 29228668, 2017). "Here, we demonstrated the anti-proliferative effects of TSC-22 in cervical cancer cells and that TSC-22 induces apoptosis linked to interaction with CSF-1R." (PMID 29228668, 2017). "The novel molecular mechanism between TSC-22 and CSF-1R suggests a potential treatment for cervical cancer." (PMID 29228668, 2017). "TSC-22 inhibits CSF-1R-dependent signaling by direct interaction, and decreases cervical cancer proliferation and migration." (PMID 29228668, 2017). "The reduction of CSF-1R protein significantly suppresses cervical cancer cell proliferation and motility and induces apoptotic cell death." (PMID 29228668, 2017). "Indeed, CSF-1R induction induced a high proliferative index and anti-apoptotic signaling in breast and cervical cancer cells." (PMID 38254773, 2024). "This study also demonstrated the involvement of PIN1 in the IL-34-mediated phosphorylation of MEK, ERK, JNK and c-Jun, while the pro-tumorigenic role of CSF-1R was mediated by its interaction with the transforming growth factor-β-stimulated clone-22 (TSC-22) protein in cervical cancer cells." (PMID 38254773, 2024). "Similarly, the reduced level of CSF1R protein significantly contributes to suppressing cervical cancer cell proliferation and motility, and induces apoptotic cell death." (PMID 33946372, 2021). "Our findings imply that TSC-22 targeting CSF-1R signaling may have therapeutic effect in cervical cancer." (PMID 29228668, 2017). "Therefore, CCR5 and CSF1R might be the new targets for cervical cancer treatment." (PMID 33946372, 2021). "In this study, we discovered CSF-1R as a new interacting partner of TSC-22 and identified its elevated expression in cervical cancer cells." (PMID 29228668, 2017). "Previous studies have identified potential marker genes (CSF1R, ERAP1, LDHA, etc.,) that may affect response rate by reshaping the cervical cancer microenvironment." (PMID 38206304, 2024).
diabetes (14 papers, 2014 to 2024). "Checkpoint inhibitors may remove the protective effects of anti-CSF-1R antibodies, leading to a greater risk in the development of diabetes; however, the MOA is poorly understood." (PMID 38606021, 2024). "GSVA showed that CSF1R/H2AFV/LCK/TLR9 is associated with various pathways related to diabetes." (PMID 35187175, 2022). "The results revealed that diabetes status was associated with methylation levels of CSF1R." (PMID 32724427, 2020). "In summary, we used a publicly available GEO dataset to perform WGCNA of immune cell infiltration in the context of diabetes and systematically identified a module related to clinical features and four hub genes (CSF1R, H2AFV, LCK, and TLR9) that may be associated with T2DM." (PMID 35187175, 2022). "Anti-colony stimulating factor-1 receptor (anti-CSF-1R) antibodies can remove diabetes-inducing macrophages to reduce the incidence of diabetes." (PMID 38606021, 2024). "Then, four hub genes related to the occurrence and development of diabetes were selected from the brown module: CSF1R, H2AFV, LCK, and TLR9." (PMID 35187175, 2022). "Furthermore, since CSF1R-stimulated microglia prevented diabetes-induced neuronal death, it is indicated that OAL-microglia in vivo can be reproduced with CSF1R-stimulated microglia." (PMID 34512619, 2021). "Type 1 diabetes mellitus and NF-κB pathway were activated in the CSF1R highly expressed group." (PMID 33564304, 2021). "Suppression of CSF1R expression both in diabetes-free and especially in diabetes tumors seems to be counter-productive for the malignancy via decreasing the influx of immunosuppressive tumor-associated macrophages (TAM) which in turn compromise antitumor activities of CD8+ cytotoxic lymphocytes." (PMID 32971867, 2020). "Therefore, the detection of CSF1R methylation levels may be a possible predictor of HCC in patients with diabetes." (PMID 32724427, 2020). "To further explore the potential functions of the hub genes in diabetes, we used their comprehensive scores for GSVA analysis, and the samples were divided into CSF1R/H2AFV/LCK/TLR9LOWand CSF1R/H2AFV/LCK/TLR9high groups." (PMID 35187175, 2022). "Thus, LCK, TLR9, CSF1R, and H2AFV are suggested to play an important role in the metabolism of patients with diabetes." (PMID 35187175, 2022). "Thus, LCK, TLR9, CSF1R, and H2AFV are suggested to play important roles in immune infiltration in subjects with diabetes." (PMID 35187175, 2022).
mesothelioma (12 papers, 2013 to 2024). A usually malignant and aggressive neoplasm of the mesothelium which is often associated with exposure to asbestos. "Studies on mesothelioma primary cultures and cell lines showed that the autocrine activation of CSF-1R characterized a pool of malignant cells with stem-like and chemo-resistant phenotypes." (PMID 38254773, 2024). "In other tumors, including mesothelioma, CSF-1R+ cells exhibited chemoresistance and expressed pluripotency-related genes." (PMID 38254773, 2024). "Inhibition of CSF-1R not only avoided mesothelioma progression and enhanced T cell response, but was also shown to increase the sensitivity of mesothelioma to PD-L1 inhibitors." (PMID 34830817, 2021). "More recently, a chemoresistant phenotype of a CSF-1R+ population of mesothelioma cells, detected in primary cultures and MPM cell lines, resulted in being supported by the expression of both IL-34 and M-CSF ligands." (PMID 34830817, 2021). "CSF-1R was shown, in more mechanistic studies, to trigger discohesive features to immortalized breast cells and resistance to pemetrexed to mesothelioma cells." (PMID 27486763, 2016). "The simple activation of CSF-1R in untransformed mesothelial cells is sufficient to confer clonogenicity and resistance to pemetrexed, hallmarks of mesothelioma." (PMID 24722292, 2014). "Additionally, in vivo studies have demonstrated the efficacy of a recently developed monoclonal antibody anti-CSF-1R (RG7155) in the reduction of CD68+/CD163+ TAMs in mesothelioma biopsies." (PMID 34830817, 2021). "Finally, lineage inappropriate expression of CSF-1R into Hodgkin's lymphoma cells and mesothelioma cells is oncogenic." (PMID 27486763, 2016). "Thus, we report a novel finding that CSF-1R expression identifies precursor-like, self-renewing mesothelioma cell sub-populations endowed with prominent protumorigenic properties, such as clonogenicity and chemoresistance." (PMID 24722292, 2014). "Thus, mesothelioma cell lines expressed all the components of the CSF-1R signaling module, implying active signaling in those cells." (PMID 24722292, 2014). "We report here increased expression of macrophage colony-stimulating-factor-1-receptor (M-CSF/CSF-1R) mRNA in mesothelioma versus normal tissue specimens and demonstrate that CSF-1R expression identifies chemoresistant cells of mesothelial nature in both primary cultures and mesothelioma cell lines." (PMID 24722292, 2014). "Therefore, we investigated the involvement of the CSF-1R/CSF-1/IL-34 system in mediating the resistance of the mesothelioma cells to pemetrexed." (PMID 24722292, 2014). "To obtain a suitable experimental system to study the CSF-1R function in mesothelioma cells, we analyzed the expression of CSF-1R and its ligands CSF-1 and IL-34 in a panel of mesothelioma cell lines and an untransformed mesothelial cell line immortalized by h-TERT (LP9)." (PMID 24722292, 2014). "Thus, targeting the IL-34, M-CSF and CSF-1R may represent a potential therapeutical approach to suppress both mesothelioma cells and pro-tumor macrophages." (PMID 34830817, 2021). "To investigate whether CSF-1R is expressed in mesothelioma tissues and if its levels are correlated to the tumor state, we performed a microarray expression analysis of 34 matched pair samples of normal peritoneal tissue versus mesotheliomas." (PMID 24722292, 2014). "M-CSFR (also known as CSF1-R) inhibitors induce the depletion of tumor infiltrating macrophages or their polarization towards a pro-inflammatory phenotype, with beneficial effects for mesothelioma regression." (PMID 34194430, 2021). "This revealed an increased mRNA expression of CSF-1R in the mesothelioma tissue as opposed to the mesothelial tissue (P<0.001)." (PMID 24722292, 2014). "In this respect, our observations indicate that both CSF-1R and AKT inhibition may be clinically relevant tools to overcome mesothelioma chemoresistance." (PMID 24722292, 2014).
mesothelioma (continued). "In murine models of mesothelioma, it was demonstrated that mesothelioma tumor cells and CD8+ upregulated PD-L1 and PD-1, respectively, in response to anti-CSF-1R therapy alone, emphasizing the importance of incorporating anti-PD-1 therapy into anti-CSF-1R treatment regimens." (PMID 35345849, 2022). "Indeed, we report increased expression of CSF-1R in mesothelioma patient samples as compared with matched normal peritoneal tissues (n=34)." (PMID 24722292, 2014).
multiple sclerosis (12 papers, 2018 to 2025). A progressive autoimmune disorder affecting the central nervous system resulting in demyelination. "Increased GM-CSF and G-CSF levels and decreased microglial Csf1r expression have also been reported in multiple sclerosis." (PMID 37964794, 2023). "CSF1R inhibition has been tested for therapeutic efficacy in mouse models for other neurological disorders such as amyotrophic lateral sclerosis and multiple sclerosis." (PMID 33685480, 2021). "They generated a selective CNS-penetrant CSF1R inhibitor molecule and observed attenuation of the inflammatory response in microglia and macrophages and significant reduction of symptoms in the animal model for multiple sclerosis." (PMID 34899694, 2021). "Targeted inhibition of CSF1R signaling has the potential to treat a wide variety of neurodegenerative diseases associated with chronic neuroinflammation such as AD, PD, Huntington’s disease, ALS, multiple sclerosis, and psychiatric disorders." (PMID 32581720, 2020). "CSF1R inhibition reduces neuroinflammation leading to improved disease phenotype in several mouse models of neurodegenerative diseases including Alzheimer’s disease and multiple sclerosis." (PMID 30386212, 2018). "Here, we review the physiological functions of CSF1R in the CNS and its pathological effects in neurological disorders including ALSP, AD, frontotemporal dementia and multiple sclerosis." (PMID 34867307, 2021).
osteoporosis (12 papers, 2012 to 2025). A condition of reduced bone mass, with decreased cortical thickness and a decrease in the number and size of the trabeculae of cancellous bone (but normal chemical composition), resulting in increased fracture incidence. "Recently, it has also been reported that anti-CSF-1R antibodies (2G2) inhibited bone loss in an osteoporosis mouse model." (PMID 32854340, 2020). "CSF1R is involved in osteoclast proliferation, and its suppression has been shown to attenuate pathological bone resorption in inflammatory arthritis, inflammatory bone destruction, and osteoporosis." (PMID 38379095, 2024). "Blockade or depletion of CSF1R suppresses the formation and activity of osteoclasts and attenuates pathological bone resorption in inflammatory arthritis, inflammatory bone destruction, and osteoporosis." (PMID 32801364, 2020). "CSF1R-mediated signaling contributes to the pathophysiology of osteoporosis, and recent studies show its potential applicability in treating bone diseases such as osteoporosis." (PMID 32801364, 2020). "In summary, these mouse data suggest that anti-CSF1R treatment could have potential in preventing or reversing age-dependent osteoporosis." (PMID 24652541, 2014). "Dual targeting of SIK2/3 and CSF1R induces bone formation without concomitantly increasing bone resorption and thereby may overcome limitations of most current anabolic osteoporosis therapies." (PMID 34160349, 2021).